INS (insulin)
Diseases named in the same sentence as INS in open-access papers (continued):
Sharing a sentence is not in itself a finding about the gene and the disease.
Hyperkalemia (continued). "This is the first comprehensive scoping review of the frequency of adverse effects following therapy with insulin for the emergency management of hyperkalaemia." (PMID 35552566, 2022). "Hyperkalemia and hypotension were managed in the ED with intravenous fluid, calcium, insulin, and dextrose." (PMID 36072186, 2022). "The patient was then started on calcium gluconate, insulin infusion, and D5-NS to treat hyperkalemia and Acidosis." (PMID 35651382, 2022). "Treatment with insulin or β-agonists are well established to lower serum potassium levels within minutes and are both used clinically for the treatment of acute hyperkalemia." (PMID 36358283, 2022). "This is the first comprehensive review of the adverse effects following insulin therapy for hyperkalaemia." (PMID 35552566, 2022). "The hyperkalemia was treated with intravenous calcium gluconate, insulin, glucose, and aggressive fluid resuscitation." (PMID 33664911, 2021). "He had promptly received emergency therapies for hyperkalemia including intravenous (IV) calcium gluconate infusion, IV sodium bicarbonate infusion, IV 10% dextrose infusion with insulin, and IV furosemide." (PMID 33938804, 2021). "The hyperkalemia, presumed to be secondary to considerable tumor manipulation, was successfully controlled with calcium, bicarbonate, and insulin with dextrose." (PMID 33842134, 2021). "Along with hyperkalemia, an increase in the C-peptide levels was also seen, indicating a decrease in hepatic cellular uptake of potassium despite insulin hypersecretion." (PMID 34725608, 2021). "In patients with symptomatic or severe hyperkalemia, treatment consists of intravenous (IV) calcium gluconate to stabilize cardiac membranes and IV glucose along with insulin to promote cellular uptake of potassium ions." (PMID 34725608, 2021). "This pilot evaluation explored the efficacy of SZC with insulin and glucose as hyperkalemia treatment in the emergency department (ED)." (PMID 32149451, 2020). "Insulin-dextrose treatment (IDT) is a common first-line treatment for moderate (potassium 6 to 7 mmol/L) to severe hyperkalemia (potassium > 7 mmol/L)." (PMID 33328554, 2020). "Overall, our study findings suggest a signal indicative of an incremental benefit of SZC when added to insulin and glucose in managing the emergency treatment of hyperkalemia." (PMID 32149451, 2020). "Our purpose was to perform a pilot evaluation to determine the efficacy of SZC combined with insulin and glucose for the emergency treatment of hyperkalemia." (PMID 32149451, 2020). "The combination of insulin and glucose is one of the most common treatments for the initial emergency treatment of hyperkalemia." (PMID 32149451, 2020). "Intravenous insulin was the most used medication for the treatment of hyperkalemia in 42 (48%) hospitalized patients, whereas 34 (39%) were treated with sodium polystyrene sulfonate." (PMID 33062520, 2020). "Rebound hyperkalemia is frequent as the combination of insulin and glucose is rarely a definitive therapy, given that its mechanism of action is to shift potassium intracellularly." (PMID 32149451, 2020). "Hyperkalemia was corrected with insulin and glucose (10 units of insulin dose with 25 g of glucose per each 1 mmol/L of potassium above the normal)." (PMID 32854648, 2020). "An ongoing phase 2 study (NCT03337477) is evaluating the short term efficiency of ZS-9 plus insulin–dextrose versus insulin–dextrose alone in patients with acute hyperkalemia." (PMID 30820692, 2019). "Insulin–glucose infusion appears to be appropriate for severe hyperkalemia due to its efficacy and reproducible lowering of serum potassium levels, with close serum glucose monitoring." (PMID 30820692, 2019). "One CoIT recipient (2.6%) and one PoIIT recipient (1.1%) experienced hyperkalemia (>5.5 mEq/L) during the intraoperative postreperfusion phase (p = 0.518), and were managed with an additional bolus insulin injection." (PMID 30390037, 2018).
Hyperkalemia (continued). "A previous animal study described that calcium administration and insulin and glucose therapy were required for hyperkalemia secondary to reperfusion injury after prolonged REBOA use." (PMID 29678197, 2018). "Perioperative hyperkalemia should be corrected with hemodialysis or intravenous infusion of a combination of insulin and high glucose." (PMID 29422012, 2018). "We identified 177 episodes where an intravenous infusion of insulin and glucose was administered to treat hyperkalemia." (PMID 28245289, 2017). "One hundred sixty four episodes of hyperkalemia were treated with insulin plus glucose and were eligible for analysis." (PMID 28245289, 2017). "There is no consensus on what is the best and safest way to administer insulin in the treatment of hyperkalemia." (PMID 28245289, 2017). "Ultimately, only a high-quality randomized control trial evaluating differences in the efficacy and safety among various regimens of insulin administration in patients with hyperkalemia can definitively answer the question as to which regimen is best." (PMID 27148740, 2016). "Our aim was to review data in the literature to determine the optimal dose and route of administration of insulin in the management of emergency hyperkalemia." (PMID 27148740, 2016). "Routine hyperkalemia therapies should be administered (insulin with dextrose, sodium bicarbonate, beta-2 agonists, calcium) promptly with follow-up doses within 2 hours if hyperkalemia, ECG changes, and weakness/paralysis have persisted." (PMID 24782897, 2014). "Throughout his stay in the ED, the patient received fluids, insulin and glucose, calcium gluconate, glucagon, and aerosolized albuterol in an effort to reverse his antihypertensive medications and hyperkalemia." (PMID 24826356, 2014). "Prescription patterns for amlodipine, calcium gluconate, hydrochlorothiazide, insulin, potassium chloride, sodium polystyrene sulfonate and spironolactone were concordant with established hyperkalemia management knowledge." (PMID 24130689, 2013). "Severe hyperkalemia was treated with oral Resonium® and an infusion of glucose and insulin (Insulin 5IE/h; 5% glucose +40 mMol Na 200 mL/h)." (PMID 24170993, 2013). "Sodium polystyrene sulfonate and insulin were used as therapeutic agents for hyperkalemia at a level of 5.00–5.50 mmol/L, and prescriptions of insulin increased rapidly beginning at a serum potassium level of 5.75–6.0 mmol/L." (PMID 24130689, 2013). "All enrolled residents responded correctly with regard to use of amlodipine, hydrochlorothiazide, insulin, potassium chloride, and spironolactone for a hyperkalemia event." (PMID 24130689, 2013). "Patients with hyperglycemia can be given insulin alone to avoid worsening of hyperkalemia by hyperosmolar state." (PMID 23882341, 2011). "Hyperkalemia is treated in the standard manner with Kayexelate, insulin/glucose, sodium bicarbonate, or albuterol as needed." (PMID 20485578, 2009). "Therapeutic options for treating hyperkalemia are calcium infusion, insulin and dextrose infusion, Sodium polystyrene sulfonate (Kayexalate) resins orally or suppository and dialysis therapy." (PMID 18845006, 2008). "Electrolyte imbalances, particularly hyperkalemia, occur due to Na+/K+-ATPase inhibition and require urgent correction with calcium gluconate, insulin with dextrose, sodium bicarbonate, or β-agonists, while hemodialysis may be necessary for refractory cases." (PMID 40137888, 2025). "During and after the administration of these treatments the patient remained hemodynamically instable, bradycardia worsened to 35 beats per minute, and hyperkalemia persisted (>6.3 mmol/L) despite continuous epinephrine infusion and the administration of bicarbonate and insulin." (PMID 40687894, 2025). "However, the combination of a deteriorated renal function and worsening bradycardia and hyperkalemia despite the administration of insulin, glucose and calcium gluconate, strengthened digoxin toxicity as working diagnosis." (PMID 40687894, 2025).
Hyperkalemia (continued). "Only loop diuretics and exchange resins remove potassium from the body, while all other ways of treatment of hyperkalaemia either shift potassium into cells (salbutamol, sodium bicarbonate, glucose insulin infusion) or stabilise the myocardium (intravenous calcium)." (PMID 40150621, 2025). "In patients receiving insulin–dextrose infusions for the treatment of hyperkalaemia, the median time from the first infusion to the first emergency HD session in the control group was 2.9 days (IQR 2.1–5.7) compared with 3.1 days (IQR 2.4–6.3) in the treatment group." (PMID 39669394, 2024). "All patients received 10 units of intravenous insulin for the management of hyperkalemia." (PMID 39274318, 2024). "Thus, comparing potassium and glucose levels after insulin administration can provide insights into the impact of hemodialysis and other factors on its efficacy and safety when treating patients with hyperkalemia." (PMID 39274318, 2024). "Hyperkalemia should be treated with calcium for maintaining cardiac function, insulin and sodium bicarbonate for the transcellular shift of potassium into cells, diuretic for lowering potassium, and hemodialysis for eliminating potassium in patients with impaired renal function or arrhythmias." (PMID 38799756, 2024). "The reduction in insulin use in 2021 was associated with a rise in the use of SZC, for which there were 66 treatment initiations, (varying in length with a total of 208 single administrations in 58 patients) for the acute treatment of hyperkalaemia." (PMID 38871123, 2024). "For example, an insulin-glucose infusion, an intravenous calcium injection, or an inhalation of a beta-2-agonist are all treatments for hyperkalemia (high potassium) that could be administered." (PMID 38961109, 2024). "Following pancreatectomy, the abrupt decrease in insulin can result in hyperkalemia." (PMID 39595353, 2024). "Our population’s high rates of insulin use represent a marker for more advanced contributing comorbidities such as DM, which may induce hyperkalemia through developing type IV renal tubular acidosis." (PMID 35619089, 2022). "The main agents used to correct the serum potassium levels and correcting hyperkalemia include the administration of intravenous insulin and glucose, cation resins such as sodium polystyrene sulfate (SPS), sodium zirconium cyclosilicate (SZC) and the combination of two or more treatment measures." (PMID 35879718, 2022). "Management of hyperkalemia involves IV calcium, insulin + D50, and beta-agonists." (PMID 36072186, 2022). "Therefore, the use of intestinal potassium excreting drugs or glucose plus insulin to promote the transfer of potassium ions into cells have gained much attention for the treatment of hyperkalemia in most MHD patients." (PMID 35879718, 2022). "In addition, even though administration of insulin and calcium was performed, electrolyte disturbances of hyperkalemia and hypocalcemia with prolongation of QTc interval occurred." (PMID 33936817, 2021). "The management of hyperkalemia with insulin–glucose/dextrose treatment (IDT) may be influenced by patient factors and cotreatments." (PMID 36417187, 2021). "Initial nephrology consultation on admission had recommended correction of metabolic acidosis and treatment of hyperkalemia with more isotonic sodium bicarbonate infusions, insulin/glucose infusions, and the initiation of oral sodium zirconium cyclosilicate (SZC)." (PMID 33938804, 2021). "This pilot study suggested that SZC with insulin and glucose may provide an incremental benefit in the emergency treatment of hyperkalemia over insulin and glucose alone." (PMID 32149451, 2020). "Insulin was the most used medication for the treatment of hyperkalemia." (PMID 33062520, 2020).
Hyperkalemia (continued). "Although the reduction of sK+ at 4 hours was similar in the sodium zirconium cyclosilicate and placebo groups, there were signals indicative of incremental benefit of sodium zirconium cyclosilicate when used in addition to insulin and glucose for the emergency treatment of hyperkalemia." (PMID 32149451, 2020). "This study demonstrates that activation of α7nAChR with Ani could ameliorate hyperkalemia during CS through E2-induced enhancement of insulin sensitivity, and thus to decrease on-site mortality." (PMID 31849684, 2019). "Comparison of clinical studies of insulin plus glucose for the treatment of hyperkalemia." (PMID 28245289, 2017). "Intravenous sodium bicarbonate was given to improve acidosis and hyperkalemia; after three courses of nebulized salbutamol, insulin, and glucose infusion, the potassium level began to decline (6.73 mmol/L) and the patient was admitted to the pediatric intensive care unit (PICU)." (PMID 26904317, 2016). "Accordingly, 10 units of short acting insulin given intravenously may be used in cases of hyperkalemia." (PMID 27148740, 2016). "Although there are multiple interventions that are used in combination to treat hyperkalemia, insulin is the mainstay of therapy in an emergency setting of hyperkalemia, where a management strategy that can quickly, and reliably lower serum K+ concentration is required." (PMID 27148740, 2016). "Recommended regimens for administration of insulin in the treatment of acute hyperkalemia." (PMID 27148740, 2016). "Although insulin levels were high, we cannot determine if rebound hyperkalemia did occur." (PMID 27148740, 2016). "We included any study that reported on the use of insulin in the management of hyperkalemia." (PMID 27148740, 2016). "To date, the current 2010 ACLS guidelines recommend the use of dextrose with insulin to treat severe hyperkalemia and suggest that insulin with dextrose can be considered for severe beta-blocker overdose, but neither support nor discourage the use of dextrose for any other condition." (PMID 25887120, 2015). "Only dextrose and insulin were administered to treat the hyperkalemia." (PMID 24932609, 2014). "Only dextrose and insulin were administered to treat the hyperkalemia because of exclusion of factors such as fluid and Na+ loading, forced diuresis and corticosteroids, which may make the pathophysiology unclear." (PMID 24932609, 2014). "Hyperkalemia was treated successfully with insulin-glucose therapy." (PMID 23668774, 2013). "Besides sodium polystyrene sulphonate resin therapy (6 g/kg/day in 8 doses), sodium bicarbonate, calcium carbonate and glucose-insulin infusions (as needed), transient peritoneal dialysis (two occasions) for severe hyperkalemia became necessary." (PMID 21750640, 2011). "The treatment of hyperkalemia is initiated by membrane stabilization with either calcium gluconate or hypertonic sodium chloride, and then by redistribution of potassium using short acting insulin and dextrose, and/or Albuterol." (PMID 20184765, 2010). "Hence, when a young child or young adult experience a sudden and apparently unexpected cardiac arrest, think of hyperkalemia, document and treat it in the standard fashion (calcium, bicarbonate, glucose and insulin, and hyperventilation)." (PMID 17456235, 2007). "Clinical data have demonstrated that a single 10‐g dose of SZC resulted in a rapid and significant reduction in sK+ as early as 1 hour after administration, suggesting that SZC may serve as an adjunct therapy to insulin and glucose in the emergency treatment of hyperkalemia." (PMID 32149451, 2020). "Thus, glucose insulin therapy started with intravenous furosemide to treat hyperkalemia." (PMID 29492442, 2017). "Insulin and glucose treatment is well known for shifting potassium to the intracellular compartment and the fact that this treatment helped raising the patient's heart rate suggests that hyperkalemia may have played a role in slowing the patient's heart rate." (PMID 24826356, 2014).
Hyperkalemia (continued). "Fasting hyperkalemia in patients with ESKD can be prevented through intravenous glucose administration, which stimulates insulin secretion." (PMID 40498214, 2025). "Unlike previous studies, which have demonstrated the benefits of SZC in conjunction with insulin/dextrose, this QIP sheds light on its use as a sole agent in acute moderate hyperkalaemia." (PMID 38871123, 2024). "Glucose-insulin therapy was initiated on DOL seven for hyperkalemia (K 7.5 mEq/L) and discontinued on DOL 15 without any recurrence of hyperkalemia." (PMID 40709124, 2025). "Initial treatments, including calcium gluconate, insulin-glucose, and sodium bicarbonate, failed to resolve hyperkalemia and/or bradycardia." (PMID 40687894, 2025). "Intraoperative dialysis was not performed, but glucose-insulin therapy was used to correct hyperkalemia in the AKI group." (PMID 40463683, 2025). "We report two cases of intraoperative hyperkalemia requiring glucose-insulin (GI) therapy during elective surgery under general anesthesia, while no hyperkalemia was observed with regional anesthesia alone in the same patients." (PMID 39717293, 2024). "Three patients with severe hyperkalemia in the control group received emergency hemodialysis or insulin and glucose treatment, while none in the experimental group required hemodialysis." (PMID 39969301, 2024). "Mostly, it is not necessary to use β2-adrenergic agonists, bicarbonate, insulin, or cation-exchange resins to correct hyperkalemia or calcium to counteract the effects of hyperkalemia on cardiac cell membranes." (PMID 38985174, 2024). "LTs uncovered: lack of insulin (an essential part of emergency treatment), lack of awareness of the hyperkalaemia protocol, and lack of knowledge on correct use of the defibrillator." (PMID 29473026, 2017). "In our review, seemingly improbable events during simulation (lack of insulin to treat hyperkalaemia and incorrect patient identification for blood transfusion) resurfaced in real life as PSIs." (PMID 29473026, 2017). "Despite the importance of insulin as a lifesaving intervention in the treatment of hyperkalemia in an emergency setting, there is no consensus on the dose or the method (bolus or infusion) of its administration." (PMID 27148740, 2016). "She developed early nonoliguric hyperkalemia and dextrose and insulin infusion (maximal at 1 U/kg/day) was administered from 8 to 30 hours after birth." (PMID 24932609, 2014). "A study of 40 preterm infants (<36 weeks) suggested the use of nebulised salbutamol may be as effective as insulin/dextrose in infants with non-oliguric hyperkalaemia with less impact on blood glucose." (PMID 35433560, 2022). "Regarding the therapeutic methods, the medical treatment based on calcium gluconate and insulin was indicated in all the patients with hyperkalemia with or without cardiac suffering, while awaiting hemodialysis due to the reduced number of the hemodialysis's “devices” available in our context." (PMID 35198181, 2022). "Although insulin–dextrose has never been tested versus placebo for the treatment of hyperkalemia, it shows similar effects on serum potassium compared with salbutamol in a study of 20 patients but with faster decrease in serum potassium with insulin (i.e., 15 vs 30 min)." (PMID 30820692, 2019). "We retrospectively reviewed charts of all AKI and non-dialysis dependent CKD patients who received 10 U of insulin plus 50 g glucose to treat hyperkalemia from December 1, 2013 to May 31, 2015 at our Department." (PMID 28245289, 2017). "In our case, even after hyperkalemia slightly improved following insulin and fluid therapy, the dog continued to exhibit complete third‐degree AV block, further supporting the premise that the cardiovascular dysfunction was primary and not the result of hyperkalemia." (PMID 41035283, 2025).